TPRG1 (tumor protein p63 regulated 1)
Synonyms: FAM79B; FLJ41238; FLJ43694
Tractability: No criterion of Open Targets' tractability assessment is met for any kind of drug.
Gene: Protein-coding gene on chromosome 3 (188,947,214 to 189,325,304, forward strand). Ensembl gene ENSG00000188001.
Subcellular location: Cytoplasm
Subcellular location (Human Protein Atlas): Nucleoplasm
Gene Ontology:
Molecular function: protein binding
Cellular component: nucleoplasm; cytoplasm
Genetic constraint (gnomAD): Loss-of-function variants: 29 observed, 30.53 expected, observed/expected ratio (o/e) 0.95, 90% interval 0.71 to 1.29. The upper end of that interval is the gene's LOEUF score, 1.29, which puts it in group 5 of 6, group 1 being the genes least tolerant of losing a copy. Missense variants: 327 observed, 347.59 expected, observed/expected ratio (o/e) 0.94, 90% interval 0.86 to 1.03. Synonymous variants: 130 observed, 123.24 expected, observed/expected ratio (o/e) 1.05, 90% interval 0.91 to 1.22.
Homologues: Orthologues: chimpanzee TPRG1 (99% identical), dog TPRG1 (91% identical), rabbit TPRG1 (88% identical), pig TPRG1 (87% identical), guinea pig TPRG1 (85% identical), mouse Tprg1 (83% identical), rat Tprg1 (82% identical), zebrafish tprg1 (42% identical), tropical clawed frog tprg1 (38% identical). Paralogues in human: TPRG1L (43% identical).
Diseases named in the same sentence as TPRG1 in open-access papers:
TPRG1 is named in the same sentence as 14 diseases in open-access papers, as found by Europe PMC text mining. Sharing a sentence is not in itself a finding about the gene and the disease. The quoted sentences say what the papers report.
breast carcinoma (4 papers, 2022 to 2024). "Tumor Protein P63 Regulated 1 (TPRG1) was found to be differentially expressed in tumor tissues including breast cancer and HPV-associated oropharyngeal squamous cell carcinoma." (PMID 34998360, 2022). "For breast cancer, we identified TPRG1, known to be enriched in breast cancer tissues, along with 25 genes upregulated in multiple cancer types." (PMID 39472583, 2024). "The significant findings included associations between self-reported history of breast cancer and hypomethylation within cg06072257 and cg06123699, which are located near UBIAD1 and TPRG1 on chromosomes 1 and 3, respectively (p = 6.5 × 10−103 and p = 2.4 × 10−101, respectively)." (PMID 37410739, 2023). "The novel associations observed in this study could strengthen evidence for candidate molecular pathways underlying peripheral disease states, e.g., self-reported history of breast cancer associated with differential methylation at cg06072257 (UBIAD1) and cg06123699 (TPRG1)." (PMID 37410739, 2023).
cystitis (3 papers, 2022 to 2025). Inflammation of the urinary bladder. "The E. coli-induced cystitis rats were then delivered with adeno-associated virus (AAV)-mediated silencing of TPRG1." (PMID 34998360, 2022). "Knockdown of TPRG1 suppressed inflammation in E. coli-induced cystitis rats, and reduced cell proliferation and migration of human pCGs through down-regulation of NF-КB/COX2/PGE2 axis." (PMID 34998360, 2022). "E. coli-induced up-regulation of TNF-α, IL-6, and IL-1β in cystitis rats were reversed by AAV-shTPRG1 injection, demonstrating that TPRG1 contributed to inflammation in E. coli-induced cystitis rat." (PMID 34998360, 2022). "This indicatest TPRG1 contributed to activation of NF-КB/COX2/PGE2 axis in E. coli-induced cystitis rat." (PMID 34998360, 2022). "Knockdown of TPRG1 decreased cell proliferation and suppressed the migration of primary cystitis glandularis cells." (PMID 34998360, 2022). "Expression of TPRG1 was also up-regulated in E. coli-induced cystitis rat compared with the sham-operated rats." (PMID 34998360, 2022). "TPRG1 promoted inflammation and NF‐КB signalling activation in a murine model of cystitis." (PMID 39723571, 2025). "Our results showed that the expression levels of TNF-α, IL-6, and IL-1β were enhanced in E. coli-induced cystitis rat, and knockdown of TPRG1 suppressed the inflammatory response in E. coli-induced cystitis rat through down-regulation of TNF-α, IL-6, and IL-1β." (PMID 34998360, 2022). "Finally, interference of COX-2 attenuated TPRG1 over-expression-induced increase in cell proliferation and migration in the primary cystitis glandularis cells." (PMID 34998360, 2022). "Secondly, TPRG1 was also increased in primary cystitis glandularis cells." (PMID 34998360, 2022). "Therefore, TPRG1 contributed to cell proliferation and migration of primary cystitis glandularis cells through up-regulation of NF-КB/COX2/PGE2 axis." (PMID 34998360, 2022). "This study found that interference of TPRG1 suppressed cell proliferation and migration of human primary cystitis glandularis cells, and ameliorated histopathological changes in bladder mucosa of cystitis rat, thus providing a potential target for the prevention of cystitis glandularis." (PMID 34998360, 2022). "Our results indicated that level of nuclear NF-κB p65 was significantly up-regulated in E. coli-induced cystitis rats, and knockdown of TPRG1 reduced the levels of COX-2 and nuclear NF-κB p65 in E. coli-induced cystitis rats and human pCGs." (PMID 34998360, 2022).
cutaneous squamous cell carcinoma (1 paper, 2020). "Of note, TPRG1 is highly expressed in normal esophageal tissue and an intergenic susceptibility locus (rs6791479) was identified in a genome-wide association study of cutaneous squamous cell carcinoma in between the TP63 and TPRG1 genes." (PMID 32252688, 2020).
diabetes (1 paper, 2024). "Our approach discovered two novel gene variants EIF4A2/ADIPOQ-rs114108468 and TPRG1-rs16864075 on 3q28 for ΔTHR among subjects without diabetes." (PMID 39557295, 2024).
diffuse large B-cell lymphoma (1 paper, 2020). "Although the function of the TPRG1 gene is not well established, amplification and/or activating mutations in Cis regulatory elements of this gene associated with its increased expression have recently been reported in diffuse large B-cell lymphomas, suggesting potential oncogenic activity." (PMID 32252688, 2020).
lung carcinoma (1 paper, 2022). "TPRG1, as an immune-related gene, was correlated with tumor recurrence of stage Ia-b lung cancer." (PMID 34998360, 2022). "Moreover, TPRG1 was considered as an immune-related gene, and correlated with tumor recurrence of stage Ia-b lung cancer." (PMID 34998360, 2022).
lymphoma (1 paper, 2021). A malignant (clonal) proliferation of B- lymphocytes or T- lymphocytes which involves the lymph nodes, bone marrow and/or extranodal sites. "In addition, amplification of TPRG1 gene was observed as an alternative mechanism of TPRG1 upregulation in DLBCL, implicating its significance in lymphoma." (PMID 34210001, 2021).
triple-negative breast carcinoma (1 paper, 2023). An invasive breast carcinoma which is negative for expression of estrogen receptor (ER), progesterone receptor (PR), and human epidermal growth factor receptor 2 (HER2). "TPRG1 encodes for Tumour protein P63 Regulated 1 and its expression is associated with estrogen receptor-positive and triple-negative breast cancers." (PMID 37410739, 2023).
tuberculosis (1 paper, 2024). A chronic, recurrent infection caused by the bacterium Mycobacterium tuberculosis. "For example, the genes upregulated in Yakutian cattle in metacarpal adipose tissue and perirenal adipose tissue, such as TPRG1 and IL20RA, suggest adaptations related to feed efficiency and susceptibility to tuberculosis, respectively." (PMID 39333243, 2024).
tumor (4 papers, 2019 to 2024). "Tumor Protein P63 Regulated 1 (TPRG1) is related to cellular inflammatory response, and dysregulation of TPRG1 in tumor tissues is associated with tumor recurrence." (PMID 34998360, 2022). "Based on Lasso regression analysis, the expressions of five immune-related genes, RLTPR, SLFN13, MIR4500HG, HYDIN and TPRG1 were closely correlated with tumor early recurrence." (PMID 34395248, 2021). "Five immune-related genes, SLFN13, RLTPR, HYDIN, MIR4500HG and TPRG1, were identified to be closely correlated with tumor early recurrence." (PMID 34395248, 2021). "There was high concordance between RLTPR (AUC: 0.71, 95%CI: 0.59-0.83), SLFN13(AUC: 0.78, 95%CI: 0.67-0.89), MIR4500HG (AUC: 0.74, 95%CI: 0.62-0.85), HYDIN (AUC: 0.72, 95%CI: 0.61-0.83) and TPRG1 (AUC: 0.75, 95%CI: 0.64-0.86) abnormal expressions and tumor early recurrence." (PMID 34395248, 2021). "Each gene can predict tumor early recurrence from many patients, which confirmed the utility of SLFN13, RLTPR, HYDIN, MIR4500HG and TPRG1." (PMID 34395248, 2021).
cancer (3 papers, 2020 to 2024). A tumor composed of atypical neoplastic, often pleomorphic cells that invade other tissues. "For example, in TPRG1 associated with HNSCC potential oncogene TP63, LPP played the role of cancer cell migration, and CCDC50 was essential for cancer cell survival." (PMID 32455963, 2020).
TPRG1 also shares sentences with these, for which no sentence is quoted: bladder tumor (1 paper); metastatic disease (1); oropharyngeal squamous cell carcinoma (1).